IL4 (interleukin 4)
Diseases named in the same sentence as IL4 in open-access papers (continued):
Sharing a sentence is not in itself a finding about the gene and the disease.
lymphedema (continued). "Lymphedematous skin from clinical biopsy specimens and mouse models of lymphedema are infiltrated with large numbers of CD4+ cells that co-express interferon gamma (IFN-γ; putative Th1 cells) and CD4+ cells that co-express interleukin 4 (IL4) or IL13 (putative Th2 cells)." (PMID 30936872, 2019). "Similarly, treatment of mice with neutralizing antibodies against IL4 or IL13, cytokines necessary for differentiation of naïve Th cells to Th2 phenotype, not only prevented the development of lymphedema in preclinical mouse models but also treated lymphedema once it was established." (PMID 34571811, 2021). "This hypothesis is supported by the fact that inhibition of Th2 differentiation with antibodies that neutralize IL4 or IL13, cytokines necessary for naïve T helper cell differentiation along the Th2 lineage, is highly effective in preventing the development of lymphedema in mouse models." (PMID 30936872, 2019). "We examined the inflammatory cytokine production in CD4+ T cells between lymphedema and post-LVA and found that IFN-γ in CD4+PD-1+ T cells and IL-17A in CD4+ T cells were downregulated post-LVA compared with that in lymphedema, while IL-4 in CD4+ T cells was not significantly different." (PMID 37250774, 2023).
abortion (18 papers, 2011 to 2025). the ending of pregnancy by removing a fetus or embryo before it can survive outside the uterus. "IL-4 and IL-10 play crucial roles in the success of pregnancy and there is strong evidence that a deficiency in IL-4 and/or IL-10 contributes to infertility, spontaneous abortion, PTB, FGR, and hypertensive disorders of pregnancy." (PMID 24904596, 2014). "The abortion-prone mouse model exhibits a dysregulated cytokine balance and downregulated levels of IL-10 and IL-4 in feto-placental units." (PMID 34298914, 2021). "In the current study, high levels of Th1 type cytokine IFN-γ were found in LPS-induced abortion mice, while the Th2 type cytokine IL-4 levels were decreased significantly when injected with LPS on day 7 of pregnancy." (PMID 20981318, 2011). "To determine whether tregitope treatment restores the Th1/Th2 balance during pregnancy in abortion-prone mice, we examined the levels of IL-2, IL-4, IL-10, IFNγ and TGFβ1 cytokines in blood sera." (PMID 32601347, 2020). "We speculate that the stable secretion of IL-4 might be due to the excessive inflammatory response in abortion condition or the intricate relationship between Tim-3-Gal-9 and IL-4 which should be probed for deeper investigation." (PMID 29651447, 2018). "However, the relevance of the early IFN-γ/IL-4 cytokine balance in the control of parasite spreading and prevention of abortion in cattle has yet to be clarified." (PMID 24479988, 2014). "However, predominant Th2 type immunity was found in abortion cases, and the typical Th2 type cytokines IL-4 and IL-10 KO mice are fertile." (PMID 23028860, 2012). "Administration of IL-4 could decrease the resorption rate in abortion prone mice." (PMID 35550500, 2022). "The cumulative evidence suggests that Treg cells and Th2 cells promote allograft tolerance by repressing Th1 and Th17 cells that are accountable for spontaneous abortion, which can secrete IL-10, TGF-β and IL-4 cytokines, respectively." (PMID 36816578, 2023). "In the present study, we cocultured PBMCs with their trophoblasts, and the PBMCs in the normal groups displayed an immune-tolerant trait characterized by the production of higher levels of IL-4 and lower IL-2 and IFN-γ than those in the abortion-prone group." (PMID 29651447, 2018). "However, the percentages of Th2 (p = 0.00001) and Th17/Th2 (producing IL-4 plus IL-17A, IL-17F and IL-22) (p = 0.001) T cell clones were significantly higher in the decidua of normal pregnancy compared to decidua of women suffering from unexplained recurrent abortion." (PMID 26798325, 2016).
breast tumor (18 papers, 2012 to 2025). "Compared to DMBA Only-treated PPARγ-WTs, both breast tumour susceptibility and serum levels of proinflammatory and chemotactic cytokines, namely IL-4, eotaxin, GM-CSF, IFN-γ, and MIP-1α, were decreased among PPARγ-MG KOs." (PMID 25889730, 2015). "In pancreatic islet cancers, breast tumors and lung metastases, interleukin-4 (IL-4) induces cathepsin protease activity in macrophages." (PMID 36670988, 2023). "Breast tumors are infiltrated by Th2 cells that strongly express IL4 and IL13, and these cytokines promote tumor growth by directly interacting with tumor cells, inhibiting DC responses and regulating the expression of cancer cell differentiation markers." (PMID 34571811, 2021). "By converting an IL-4 signal into an IL-7 signal, these T cells expanded robustly and mediated potent antitumor immunity in mice bearing breast tumors." (PMID 30842774, 2019). "Angiogenesis of human breast tumor cells has been shown to be inhibited by the addition of IL-4, preventing metastatic growth and proliferation." (PMID 30842774, 2019). "In line with this evidence, treatment with anti-IL-25 blocking antibody significantly reduced IL-4-producing CD4+ Th2 cells in the MMTV-PyMT breast tumor model." (PMID 27909985, 2017). "We found that IR-induced IL-4 signaling also promoted the growth of primary breast tumors and their metastasis to lung in nude mice by activating IL-4/JNK/β-catenin/Stat6 signaling." (PMID 27895317, 2016). "This is supported from data in the literature showing that miR-223 can be transferred to breast tumor cells from bone marrow stroma or microvesicles derived from IL-4 activated macrophages." (PMID 24400121, 2014). "In this study, we examined the changes of ILC1, ILC2, and ILC3 frequency in innate immunity, CD4+ and CD8+ T cells in adoptive immunity, and the expression of their associated cytokines (IFN-γ, IL-4, IL-10, IL-13, and IL-22) in 4T1 and MC4-L2 breast tumor models." (PMID 39877637, 2025). "Finally, a study detected miR-223-3p in exosomes released by IL-4 (interleukin-4)-activated macrophages; this miRNA has been shown to transfer to breast tumour cells where it regulates invasion through the Mef2c (myocyte enhancer factor 2C)-β-catenin pathway." (PMID 34064331, 2021). "However, since both adipose tissue and cancer cells secrete IL-4 to promote a suppressive tumor microenvironment, blocking IL-4R signaling was found to decrease the viability of breast tumor cells." (PMID 30842774, 2019). "Furthermore, IL-4 and IL-12p40 were also decreased in the breast tumors by Infliximab treatment." (PMID 38201482, 2023). "To determine whether IL-4/13 signaling mediates the effects of Th2 cells onto breast tumor cells, we implanted PyMttg or PyMttg Il4rKO primary breast tumors into the abdominal mammary fat pad of Tslptg (test) versus WT (control) mice and monitored tumor formation and growth over time." (PMID 35657353, 2022). "The earlier tumor onset did not translate into reduced survival in mice that lacked IL-4Rα, suggesting that the protective role of IL-4 is mainly in the initiation phase of breast tumor development." (PMID 35657353, 2022). "However, IL-4 and IL-13 do not directly mediate the tumor-suppressing effect of Th2 cells onto the breast tumor cells." (PMID 35657353, 2022).
cryptococcal infection (18 papers, 2010 to 2025). "Th2 responses are typically non‐protective against cryptococcal infection and are associated with the release of the inappropriate cytokines IL‐4, IL‐5 and IL‐13, which promote fungal persistence, dissemination and worsened pathology." (PMID 36175380, 2023). "Th2-type T-cell responses, characterized by production of IL-4 and IL-13 and alternative activation of macrophages, are strongly associated with adverse outcomes in mouse models of cryptococcal infection." (PMID 25853653, 2015). "Previous research has shown that suppressing the Th2 response by knocking out IL‐4, IL‐4R and IL‐13 in mice increases resistance to cryptococcal infection, with very little infiltration or persistence of fungal cells in the CNS compared to wild type." (PMID 36175380, 2023). "The IL-4-mediated Th2 response triggered by Sv exacerbated cryptococcosis and increased lethality since a lower production of proinflammatory cytokines is associated with a worsening of the fungal disease." (PMID 37888224, 2023). "While type-1 immune responses have been shown to drive protective immunity against cryptococcal infection, type 2-skewed immune responses defined by the production of IL-4, IL-5, and IL-13 play deleterious roles in infection with C. neoformans." (PMID 30520685, 2019). "In contrast, previous studies have shown that Th2 responses that are characterized by the production of interleukin-4 (IL-4) and IL-13 are detrimental during cryptococcosis (10, –, 13)." (PMID 29317510, 2018). "We further examined the effect of IFNAR1 deficiency on the Th2 response by measuring the production of IL-4, IL-5, and IL-13 in the lungs on day 3, 7, 14, and 28 after cryptococcal infection." (PMID 26384031, 2015). "In addition, Th2-type (IL-4 and IL-10) and Th17-type (IL-17) cytokines contributed, to a lesser extent, to protection against cryptococcal infection." (PMID 36557672, 2022). "Unexpectedly, however, Th2 cytokines such as IL-4 and IL-13, which suppress host defense against cryptococcal infection by inhibiting macrophage activation and enhancing mucin production, were not increased but rather also decreased in luCldn-18−/− mice compared to luCldn-18+/+ mice." (PMID 34702961, 2021). "Th2 cytokines such as IL-4 and IL-10 have been shown to have non-protective response against cryptococcal infection and are associated with poor clinical improvement." (PMID 29133871, 2017). "Since Th1, rather than Th2 responses, are protective in cryptococcosis, a Th2 response to cryptococcus characterized by increased IL-4 production by T cells might be associated with ineffective antigen clearance, leading to a predisposition to the subsequent development of IRIS." (PMID 21253011, 2010). "In contrast, administration of recombinant IFN-αA/D significantly suppressed the production of IL-4, but not of IFN-γ and IL-17A, in the lungs of WT mice after cryptococcal infection." (PMID 26384031, 2015).
cyst (18 papers, 2012 to 2025). A sac-like closed membranous structure that may be empty or contain fluid or amorphous material. "Compared with BALB/c mice, FVB mice is a more favorable host for C. sinensis on the basis of cyst formation in bile ducts because they have increased production of Th2-associated anti-inflammatory cytokines, including IL-4, IL-5, IL-13, IL-10 and TGF-β." (PMID 28784165, 2017). "However, when explored after in-vitro stimulation, we showed that the IL-4-specific-response using a whole-blood platform associated with cyst activity." (PMID 34415898, 2021). "The cyst fluid markers that were used were MMP9, CA72-4, sFASL, and IL-4, which were overproduced in high-risk IPMN patients (p < 0.05)." (PMID 39594780, 2024). "The levels of IFN-γ, IL-1β, IL-2, IL-4, IL-10, IL-12, and IL-13, in contrast, were significantly higher in pus than in cyst fluid." (PMID 35965529, 2022). "But during cyst establishment and growth, there is a switch to a Th2 response by secreted IL-4, IL-5, IL-6, IL-10 and so on, which is beneficial to parasite survival." (PMID 35360110, 2022). "In mice model, IFN-γ and IL-12 enhanced Th1 immune response and decreased the cyst load index, whereas IL-4 boost Th2 immune response and increased the cyst load index." (PMID 34818327, 2021). "We evaluated the accuracy of a whole-blood stimulation test based on Interleukin (IL)-4 detection in response to Antigen B (AgB) of Echinococcus granulosus sensu lato to discriminate cyst viability and detect cyst reactivation in patients with hepatic CE." (PMID 34415898, 2021). "The 2 sets of markers (MMP9 and CA 72-4, sFASL and IL-4) were evaluated in the cyst fluid samples of 149 patients across 3 high volume institutions, with reported concordance indices of 0.76 and 0.8, respectively." (PMID 32050465, 2020). "In nonpregnant mice infected with T. gondii, IL-4 deficiency increased mortality, but reduced the brain tissue cyst burden." (PMID 34675905, 2021). "IL-4 can modify intracellular replication and prevent cyst formation in the brain, and thus, the high level of IL-4 may shed light on the reduced number of brain cysts in chronic infection." (PMID 31456786, 2019). "Together with the overproduction of IL-4, IL-5, and IL-13, these cytokines may mount a response that could destroy the T. saginata PO form and prevents development of the cyst in vivo." (PMID 30870421, 2019). "Detection of specific cytokines and their fluctuation (e.g., IL-4;) could have potential in the definition of cyst vitality (viability) and follow-up of treated patients, with limitations regarding test sensitivity and available facilities." (PMID 30188936, 2018). "With the exception of the association of IL-4 and IL-13 with the cyst stage, all other cytokines did not associate with cyst stages." (PMID 25429386, 2014). "Our data suggest that the presence of cyst antigens induces alternative activation of macrophages and that these antigens are required for macrophages to produce chitinase even in the presence of IL-4." (PMID 23209401, 2012). "In turn, IL-4 stimulates LTC4 generation and cyst-LTs release, including LTC4, while IL-10 enhances LTB4 production and release." (PMID 39843578, 2025). "With the growing body of literature on highly correlative biomarkers identified in cyst fluid analysis, the same research group sought to combine their nomogram with their proteomic biomarker models MMP9 and CA 72-4, sFASL, and IL-4." (PMID 32050465, 2020). "The results showed that IL-4 measurement is not informative enough of cyst viability and reactivation to be used in clinical practice." (PMID 34415898, 2021). "Importantly, addition of cysts or cyst antigen but not “naked” bradyzoites, did lead to a significant increase in urea production although not as great as induction of alternative activation by IL-4." (PMID 23209401, 2012).
Erythema (18 papers, 2015 to 2026). Redness of the skin, caused by hyperemia of the capillaries in the lower layers of the skin. "Clinical symptoms, including erythema, edema, and crusting, were monitored, and serum levels of IL-4, IL-13, IgE, and histamine were quantified using ELISA." (PMID 41646846, 2026). "DSMs, especially in cream form, showed promising therapeutic effects by reducing AD-like lesion formation, trans-epidermal water loss, erythema, serum IgE, IFN-γ, and IL-4 levels, and skin thickness." (PMID 40299438, 2025). "In the current study, we repeatedly applied DNCB to the dorsum skin of SKH-1 hairless mice to induce AD-like skin symptoms, such as severe erythema, lichenification, mast cell infiltration, and the overexpressions of serum IL-4 and IgE." (PMID 37107248, 2023). "The erythema, barrier function, and epidermal thickness of the AD-like wounds were improved by CoQ0 through the reduction of IL-1β, IL-4, IL-6, IL-10, interferon (IFN)-γ, and by neutrophil infiltration in the lesional skin." (PMID 31849685, 2019). "In AD or PN with prominent erythema and barrier dysfunction—where IL-4 and IL-13 are likely elevated—nemolizumab may transiently increase TARC and activate Th2 responses, raising the risk of Th2-related AEs." (PMID 40364058, 2025). "IL-4 plays a crucial role in the pathogenesis of AD via Th2 immunity, IgE switch, and mast cell and eosinophil recruitment, which are involved in itching, dryness and erythema during allergic antigens exposure." (PMID 36908272, 2023). "If the IFN-γ level in spleen lymphocytes (showing erythema on the ELISpot board) is significantly more than the IL-4 level (showing blue spots in ELISpot board), the type of immune response stimulated was Th1, namely, to activate CD8+T lymphocytes and mainly the body’s CTL response." (PMID 30120629, 2018). "Hence, we suggest that DBT has an effect on the regulation of cytokine IL-4 expression and mast cell infiltration to improve AD-like syndromes in the skin, including erythema, edema, skin cracking, and fluid leakage." (PMID 25861366, 2015). "Edematous erythema and erythematous papules may develop not only as manifestations of type IV hypersensitivity reactions—such as drug-specific T-cell sensitization or hapten formation—but also as a result of cytokine imbalances, particularly the upregulation of IL-4." (PMID 40364058, 2025). "Topical chamaejasmine application impressively reduced erythema, edema, erosion, dryness, and lichenification, in our SKH-1 mouse model by suppressing serum IgE and IL-4 levels." (PMID 31694198, 2019). "Kif3aK14∆/∆ mice skin appeared normal without lesions or erythema by H&E staining and no baseline inflammation was observed in the skin by IL-4 and IL-13 qPCR, and CD3 staining." (PMID 32796837, 2020). "PPD induration and EC erythema revealed upregulated expression of IFN-γ and TNF-α compared with the PBS group, while no increases were seen in IL-4 expression, thus indicating that Th1 cytokines were mainly expressed in PPD induration and EC erythema." (PMID 38068935, 2023).